PPIAL4D (peptidylprolyl isomerase A like 4D)
Description:
PPIases accelerate the folding of proteins. It catalyzes the cis-trans isomerization of proline imidic peptide bonds in oligopeptides (By similarity).
Tractability: No criterion of Open Targets' tractability assessment is met for any kind of drug.
Gene: Protein-coding gene on chromosome 1 (145,241,415 to 145,242,174, reverse strand). Ensembl gene ENSG00000289549.
Subcellular location: Cytoplasm
Gene Ontology:
Molecular function: cyclosporin A binding; peptidyl-prolyl cis-trans isomerase activity
Biological process: protein folding
Cellular component: cytoplasm
Genetic constraint (gnomAD): Loss-of-function variants: 0 observed, 2.28 expected, observed/expected ratio (o/e) 0, 90% interval 0 to 1.23. That is too few expected variants to judge how well the gene tolerates losing a copy. Missense variants: 0 observed, 43.21 expected, observed/expected ratio (o/e) 0, 90% interval 0 to 0.069. Synonymous variants: 0 observed, 13.48 expected, observed/expected ratio (o/e) 0, 90% interval 0 to 0.22.
Homologues: Orthologues: zebrafish ppiab (68% identical), zebrafish ppifa (68% identical), Caenorhabditis elegans cyn-3 (65% identical), Caenorhabditis elegans cyn-7 (65% identical), zebrafish ppiaa (64% identical), Caenorhabditis elegans cyn-2 (63% identical), Caenorhabditis elegans cyn-1 (60% identical), Caenorhabditis elegans cyn-9 (49% identical), Drosophila melanogaster Cyp40 (48% identical), Drosophila melanogaster Moca-cyp (46% identical). Paralogues in human: PPIAL4E (99% identical), PPIAL4F (99% identical), PPIAL4C (98% identical), PPIAL4A (97% identical), PPIAL4G (96% identical), PPIAL4H (96% identical), PPIA (84% identical), PPIF (66% identical), PPIE (61% identical), PPID (60% identical), PPIB (56% identical), PPIC (53% identical), and 10 more.